MAPK14 (mitogen-activated protein kinase 14)
Diseases named in the same sentence as MAPK14 in open-access papers (continued):
Sharing a sentence is not in itself a finding about the gene and the disease.
cataract (1 paper, 2022). Partial or complete opacity of the crystalline lens of one or both eyes that decreases visual acuity and eventually results in blindness. "MAPK14 plays an important role in cataract formation, owing to the activation of MAPK14 which can lead to the induction of cataracts." (PMID 35860180, 2022). "Four genes, including ESR1, MAPK14, CASP3, and AKR1B1, were shared between CS compound targets and cataracts' targets, indicating their possible anticataract action." (PMID 35860180, 2022). "Network analysis suggested that four shared targets may play crucial roles in the treatment of cataracts, including aldose reductase (AKR1B1), caspase-3 (CASP3), mitogen-activated protein kinase 14 (MAPK14), and estrogen receptor (ESR1)." (PMID 35860180, 2022). "Although the gene expression of MAPK14 and AKR1B1 was not affected by CS treatment, the activities of these proteins required further validation to identify their roles in the treatment of cataracts by CS." (PMID 35860180, 2022).
Chlamydiae infection (1 paper, 2017). "Similarly, upregulation of MAPK14 by Chlamydiae infection in host cells seems to be another mechanism by which these bacteria could disrupt effecter phenotype of macrophages." (PMID 29375545, 2017).
chronic hepatitis (1 paper, 2018). An active inflammatory process affecting the liver for more than six months. "MAP2K7 and MAPK14 were highly expressed in chronic hepatitis; LAT, SOS2, and BCL‐10 were highly expressed in normal tissues; PTPN6, LCK, and CTLA4 were highly expressed in CS." (PMID 30259695, 2018).
coronary artery disease (1 paper, 2021). "CSF3, IL-1A, CCR7, IL-18, and MAPK14, as well as IL-17 signaling pathway and cytokine and cytokine receptor interaction signaling pathway related with inflammatory response might be the potential biomarker and targets for the treatment of coronary artery disease." (PMID 33777109, 2021).
craniosynostosis (1 paper, 2025). Craniosynostosis is defined as the premature fusion of one or more cranial sutures leading to secondary distortion of skull shape resulting in skull deformities with a variable presentation. "Our evidence supports p38α MAPK as a potential therapeutic target for craniosynostosis, as pharmacological or genetic attenuation of p38α MAPK and conditional knockout (cKO) of Mapk14 effectively prevents SPC senescence, mitigates suture fusion and craniofacial deformities in Crouzon mice." (PMID 41390905, 2025). "Given the predominance of Prrx1+ cells within the cranial suture mesenchymal cell population and their significant overlap with other suture stem cell populations, this study employed Prrx1+ cell-specific Mapk14 cKO to prevent SPC senescence and ameliorate craniosynostosis." (PMID 41390905, 2025).
cyst (1 paper, 2025). A sac-like closed membranous structure that may be empty or contain fluid or amorphous material. "However, in Villin-Cre; TSC1f/f mice, the deletion of MAPK14 further enlarged kidney size, increased cyst formation, and worsened renal secretion issues." (PMID 40854626, 2025).
delirium (1 paper, 2023). A disorder characterized by confusion; inattentiveness; disorientation; illusions; hallucinations; agitation; and in some instances autonomic nervous system overactivity. "The reported MAPK signaling pathway-related hub proteins, namely MAPK1, MAPK3 and MAPK14, might be involved in delirium-associated neurological disorders/activities which demand deeper investigation." (PMID 37993790, 2023). "The MAPK signaling pathways might be crucial for delirium pathophysiology since the key delirium-associated hub proteins MAPK1, MAPK3, and MAPK14 were found to be associated with it." (PMID 37993790, 2023).
fibromyalgia (1 paper, 2014). A chronic disorder of unknown etiology characterized by pain, stiffness, and tenderness in the muscles of neck, shoulders, back, hips, arms, and legs. "Fibromyalgia has been genetically linked to the HLA region (6p21.3) 63, which includes several genes associated with Notch signalling (e.g. Notch4, FKBP5, TNXB, MTCH1 and TNF-a) or with stem cell maintenance and proliferation (e.g. POU5F1, Flot1, MAPK14, Rgl2 and Rab44)." (PMID 25164209, 2014).
graft versus host disease (1 paper, 2023). An immune system disorder that occurs after allogeneic hematopoietic stem cell transplant and is a reaction of donor immune cells against host tissues. "MAPK14 was related to graft versus host disease, and primary immunodeficiency." (PMID 37928394, 2023).
head and neck cancer (1 paper, 2023). A primary or metastatic malignant neoplasm affecting the head and neck. "More specifically, DUSP16 has been shown to interact with MAPK14, which is involved in lymphangiogenesis, angiogenesis, and cell proliferation in head and neck cancer and cancer cells growth control." (PMID 37887710, 2023).
hemangioma (1 paper, 2022). A benign vascular lesion characterized by the formation of capillary-sized or cavernous vascular channels. "It was found that MAPK14 was upregulated in proliferating hemangioma and showed downregulation in involuting hemangioma." (PMID 35740845, 2022). "Mitogen-activated protein kinase 14 (MAPK14) was identified as having different expression in proliferating and involuting hemangiomas." (PMID 35740845, 2022). "Proliferating hemangioma had MAPK14 and AKT1 gene upregulation and ACTA2 downregulation." (PMID 35740845, 2022). "In our study, we detected an upregulation of MAPK14, a member of the MAPK family, in a case of proliferating hemangioma (not yet reported in the literature) together with AKT1 upregulation." (PMID 35740845, 2022).
hyperandrogenism (1 paper, 2022). Excessive secretion of androgens from the adrenal glands or gonads. "Considering that androgen excess in women impairs hepatic glucose metabolism by decreasing insulin-stimulated glucose uptake and glycogen synthesis, the MAPK14 pathway may be a nexus between IR and hyperandrogenism that is triggered by oxidative stress." (PMID 36498989, 2022).
hypertensive nephropathy (1 paper, 2025). Kidney damage that results from chronically elevated blood pressure; complications include glomerular damage resulting in proteinuria and hematuria. "Critically, this review illuminates unique and novel mechanisms, including the enhancement of autophagy by Acteoside and the targeted inhibition of the AT1R/MAPK14/IL-17 axis by Rehmannioside A in hypertensive nephropathy." (PMID 41333019, 2025).
infantile hemangiomas (1 paper, 2022). "In our study, involuting infantile hemangioma was characterized by downregulation of p38/MAPK14 and upregulation of the ACTA2 gene." (PMID 35740845, 2022). "The role of MAPK14 in infantile hemangiomas is incompletely elucidated, with most of the data being derived from a few experimental studies." (PMID 35740845, 2022). "MAPK14 was downregulated in involuting infantile hemangioma." (PMID 35740845, 2022). "In this way, MAPK14 may play a dual role in infantile hemangioma pathogenesis and may potentiate the incomplete response and recurrences that sometimes follow after propranolol treatment in proliferating infantile hemangiomas." (PMID 35740845, 2022). "Involuting infantile hemangioma was characterized by ACTA2 upregulation and AKT1 and MAPK14 downregulation." (PMID 35740845, 2022).
knee osteoarthritis (1 paper, 2023).
leiomyoma (1 paper, 2021). A well-circumscribed benign smooth muscle neoplasm characterized by the presence of spindle cells with cigar-shaped nuclei, interlacing fascicles, and a whorled pattern. "On the contrary, researches of MAPK14 related to SMCs showed that VSMC differentiation and proliferation were inhibited both in vivo and in vitro, which is in accordance with human leiomyoma cells." (PMID 34513945, 2021).
leprosy (1 paper, 2022). Leprosy is a chronic infectious disease affecting primarily the skin and peripheral nervous system. "We also described a molecular signature associated with neural damage in early stages of pure neural leprosy from patients (i.e., HLA-DRB1, MAPK14, GAP43, FABP7, NTN1, and LRRTM4)." (PMID 35492305, 2022). "However, there is a lack of information regarding MAPK14 in leprosy." (PMID 35492305, 2022).
lung adenocarcinoma (1 paper, 2025). A carcinoma that arises from the lung and is characterized by the presence of malignant glandular epithelial cells. "Dauriporphine inhibited cell growth, metastasis, and glycolysis-related energy metabolism of lung adenocarcinoma cells via modulating miR-424-5p/MAPK14 axis." (PMID 40500789, 2025). "Dauriporphine can be considered in drug development for lung adenocarcinoma, with the miR-424-5p/MAPK14 axis as the therapeutic target." (PMID 40500789, 2025). "The targeting relationship between miR-424-5p and MAPK14 was revealed in LPS-induced lung injury, which was also confirmed in lung adenocarcinoma cells in the present study." (PMID 40500789, 2025). "Silencing miR-424-5p significantly elevated the expression of MAPK14 in dauriporphine-treated A549 cells, while downregulating MAPK14 not only reversed the effect of miR-424-5p on its expression but also reversed the protective effect of miR-424-5p on dauriporphine-treated lung adenocarcinoma cells." (PMID 40500789, 2025). "Therefore, dauriporphine was hypothesized to inhibit the progression of lung adenocarcinoma through the miR-424-5p/MAPK14 axis." (PMID 40500789, 2025).
lung diseases (1 paper, 2024). "A recent study demonstrated that nine genes (CD274, CEACAM1, CR1, FCGR1A/B, IFITM1, IRAK3, LILRA6, MAPK14, and PDCD1LG2) showed 100% sensitivity and specificity that distinguished patients with active TB from those with other lung diseases (OPD)." (PMID 38674369, 2024).
lung neoplasm (1 paper, 2020). A benign or malignant, primary or metastatic neoplasm involving the lungs. "For instance, SF(Pkinase, Death) contains seven members (MAP3K8, MAPK3, MAPK14, MAPK1, AKT1, CHEK2, and DAPK1) that are related to lung neoplasms." (PMID 31937869, 2020).
Ovarian cyst (1 paper, 2021). The presence of one or more cysts of the ovary. "Our result suggested that Jingshu granules may promote ovulation by targeting MAPK14 in the VEGF signaling pathway in the therapy of ovarian cysts." (PMID 33623786, 2021).
pancreatic adenocarcinoma (1 paper, 2021). "Likewise, activated MAPK14 is considered as a druggable target in cancer including pancreatic adenocarcinoma." (PMID 33803354, 2021).
primary hypertension (1 paper, 2022). "Among them, AGTR1, AKT1 with puerarin, EDNRA with tanshinone IIA, MAPK14 with daidzein, MAPK8 with ursolic acid, and CHRM2 with cryptotanshinone all have a strong correlation with GJD in the treatment of primary hypertension." (PMID 36046450, 2022). "The research uncovered that the key active ingredients of GJD in managing primary hypertension are puerarin, tanshinone IIA, daidzein, ursolic acid, and cryptotanshinone, which are mainly expected to contain a regulatory function in conjunction with AGTR1, AKT1, EDNRA, MAPK14, MAPK8, and CHRM2." (PMID 36046450, 2022).
primary myelofibrosis (1 paper, 2021). Myelofibrosis with myeloid metaplasia is a myeloproliferative disease with annual incidence of approximately 1 case per 100,000 individuals and age at diagnosis around 60 (an increased prevalence is noted in Ashkenazi Jews). "External datasets validated that the MAPK14 expression was significantly higher in PV than that of essential thrombocytosis (ET)/primary myelofibrosis (PMF) patients and normal donors." (PMID 34059095, 2021).
rheumatic diseases (1 paper, 2018). "Decreases of Mapk14 and Prkcg mRNA levels following FAAH inhibition highlights hopes for new treatment strategies of neuropathic components in rheumatic diseases, as seen with intrathecal administration of p38α MAPK and PKCγ inhibitors in a chronic constriction injury model of neuropathic pain." (PMID 29364174, 2018).
subarachnoid hemorrhage (1 paper, 2019). A serious neurological disorder characterized by intracranial hemorrhage into the subarachnoid space. "Other greenyellow hubs were associated with endothelin-1 signaling (PLBD1, MAPK14, CASP4), which is implicated in cerebral vasospasm following subarachnoid hemorrhage." (PMID 30836997, 2019).
cancer (152 papers, 2008 to 2026). A tumor composed of atypical neoplastic, often pleomorphic cells that invade other tissues. "Historically, research has investigated that MAPK1 and MAPK14 were associated with cancer risk and survival in CRC." (PMID 34381520, 2021). "We recognize a truncated variant of MAPK14, called Mxi-2, being overexpressed in the malignant tumors." (PMID 30214689, 2018). "Prunin could inhibit the proliferation and migration of cancer cells, possibly by downregulating MAPK14 expression, which is linked to poor prognosis." (PMID 40141319, 2025). "Moreover, MBZ can modulate various cancer-associated pathways, including MAPK14, MEK-ERK, C-MYC, USP5/c-Maf, TNIK, XIAP, ELK/SRF, NFKB, MYC/MAX, E2F/DP1, TGF/SMAD, AP1, and STAT1/2, dependent on the specific cancer model." (PMID 36674870, 2023). "Network pharmacology analysis, molecular docking, and molecular dynamics simulations identified MAPK14 (p38α), a pharmacological target leading to cancer cell apoptosis, as a putative target." (PMID 38727308, 2024). "Our results also corroborate earlier reports showing the therapeutic effects of small molecules on cancer cell proliferation and apoptosis through the MAPK14 pathway." (PMID 38727308, 2024). "Conversely, other studies have shown that the 5-FU therapeutic response is regulated by the balance between apoptosis and autophagy in cancer cells, which is regulated by mitogen-activated protein kinase 14 (MAPK14)/p38 activation." (PMID 37108476, 2023). "This is because MAPK14 plays a role in cancer cell migration, tumour invasion, and metastasis, where the expression of matrix metalloproteinases (MMPs) and angiogenic factors is induced by p38 MAPK signalling." (PMID 37686122, 2023). "depicted for the first time, that CEBPA is involved in chemotherapeutic resistance and cancer stemness by affecting the MAPK14/C/EBPα signaling pathway in BC." (PMID 37483521, 2023). "This study suggests that targeting MAPK14 with MBZ is a promising strategy to enhance chemotherapy efficacy against GBM cancer." (PMID 36674870, 2023). "MAPK14 was expressed about three-fold higher in the cancer cells, and transcription was upregulated by DEX treatment in both FTC-133 cells and Nthy-ori 3-1 cells." (PMID 36980530, 2023). "On the other hand, MAPK13 (p38δ) and MAPK14 (p38α) expression levels are significantly higher in the primary tumor in most cancers." (PMID 35501462, 2022). "Growing evidence has shown that Mapk14 plays a critical role in the occurrence and progression of multiple human cancers, including CRC." (PMID 35141222, 2022). "To investigate the possible role of Mapk14 in carcinogenesis, we first analyzed its expression in 16 human cancers." (PMID 35141222, 2022). "It was demonstrated that MARK1 and MAPK14 can affect the multiplication and apoptosis in cancer cells." (PMID 36003525, 2022). "MAPK14, hSP90AA1, and PTGS2 genes are associated with apoptotic biological processes, TNF signaling pathways, toll-like receptor signaling pathways, and cancer pathways." (PMID 36212968, 2022). "As a member of MAPK family, MAPK14 plays a vital role in the regulation of apoptosis, MAPK14 is also overexpressed in breast, ovary and cancer cells to promote tumorigenesis and development." (PMID 36532716, 2022). "The genes MAPK14, HSP90AA1, PTGS2, and ESR1 have been linked to cancer, infection, and immune disease." (PMID 36212968, 2022). "Studies have shown that Mapk14 overexpression in breast, ovarian, and cancer cells promotes tumorigenesis and progression." (PMID 35141222, 2022). "We also identified another 40 MAPK pathway genes (including MAPK1, BRAF and MAPK14) that are classifiable as “strongly selective” (see the “Methods” section) across various cancer cell lines." (PMID 33398072, 2021). "On the other side, ROS-dependent activation of MAPK14 (mitogen-activated protein kinase 14) during starvation limits excessive autophagy activation in order to protect cancer cells against stress-induced cell death." (PMID 32635505, 2020).